IFNG (interferon gamma)
Diseases named in the same sentence as IFNG in open-access papers (continued):
Sharing a sentence is not in itself a finding about the gene and the disease.
tumor (continued). "Similarly, adenoviral delivery of XCL1 and tumor-associated antigens to DC increases IL-2 and IFNγ production by NK and T cell populations." (PMID 30979057, 2019). "Mechanisms of tumor-intrinsic acquired resistance include decreases in and loss of neoantigens, disruption of neoantigen presentation, and resistance to interferon gamma." (PMID 30458888, 2018). "Such difference effects could be due to the fact that LNT treatments suppress tumor angiogenesis via increasing IFNγ production, which is associated with the accumulation of IFNγ-expressing neutrophils." (PMID 30373628, 2018). "Accordingly, T cells fail to migrate to tumor site in IFNγ-deficient mice." (PMID 29780381, 2018). "Loss of PTPN2 sensitizes the tumor to immunotherapy via IFNγ signaling." (PMID 29764444, 2018). "It is intriguing to speculate that it might be the cytokine production within the tumor microenvironment that causes the expression of ICAM1 in the tumor cells, since TNFα and IFNγ are known to induce synthesis of ICAM147." (PMID 30082828, 2018). "However, despite the fact that also other cells express Ifnγ and Il17a, the examination of T-cell effector molecules revealed decreased Ifnγ and Il17a expression in obese IL-6Rα-deficient tumours that have been restored upon Treg depletion." (PMID 29695802, 2018). "The IFNG-rs1861494 polymorphism was successfully integrated in a previously published clinical-genetic score including other clinical risk factors (i.e., gender, primary tumor site, and tumor stage) and the patient’s genotype for MTHFR-rs1801131." (PMID 30337874, 2018). "Moreover, IFNγ and IL-2 production in response to tumor recognition were reduced when Y206 and Y209 were mutated with either of both alanine or glutamic-acid residues." (PMID 30400835, 2018). "Various biomarkers such as mutational burden, the presence of tumor-infiltrating lymphocytes, and interferon-gamma signature have been suggested for predicting the response to anti-PD-1/PD-L1 inhibitors; among these, PD-L1 expression in tumor cells is a promising and simple predictive biomarker." (PMID 29228662, 2017). "While it may seem paradoxical that an immunosuppressive molecule should show these favorable associations, it is now recognized that TIL can induce tumor cell PD-L1 expression by producing cytokines such as interferon gamma (IFN γ)." (PMID 28881675, 2017). "However, some tumor samples with JAK1 frameshift mutations in the TCGA dataset exhibited high expression of IFNγ response genes." (PMID 29121062, 2017). "Thus IFNγ has been established to have dual role: one as a hallmark of anti-tumor immunity and another to support tumor growth by immune escape phenomena, a mechanism mediated through PD-L-1 expression." (PMID 28512255, 2017). "However, in case of JAK1/2 deficiency IFNγ-induced restoration of antigen presentation in tumour cells is abrogated." (PMID 28561041, 2017). "Similarly, while IFNG exerts clear anti-tumorigenic functions it appears to be also implicated in tumor progression in some settings." (PMID 29212506, 2017). "Assuming that the disconnect between the predicted and observed dynamic change in IFNG gene expression is driven by an underlying biological process, we created a revised model (V3) that changed the representation of tumor-infiltrating lymphocytes from one state to four states." (PMID 28101055, 2016). "This local association might be explained by an induction of PD-L1 in tumor cells by infiltrating lymphocytes which are known to be a source of interferon-gamma." (PMID 26517811, 2015). "Thus, Th17 cells have been implicated in promoting tumour through producing angiogenic factors but, paradoxically, also shown to counteract tumour development by producing IL-17 and IFNγ." (PMID 26101460, 2015). "Moreover, α4-1BB antibody therapy is dependent on IFNγ, as CD8 T cells were incapable of trafficking to the tumor site in IFNγ-deficient mice." (PMID 26106583, 2015).
tumor (continued). "Activation of NK cells by this tumor cell line appears to be caused by a classical “missing self” recognition since both activation and NK cell cytotoxicity are greatly reduced by IFNγ–induced MHC class I up-regulation on B16 cells prior to exposure to NK cells (and data not shown)." (PMID 25101668, 2014). "IFNγ is implicated in tumor proliferation via activation of the Shh signaling pathway in various tissues but whether a similar mechanism exists in the stomach is unknown." (PMID 24069395, 2013). "HPV16 encodes the two tumor-specific oncoproteins E6 and E7 that can elicit a favorable immune response, in which virus-specific interferon-γ (IFNγ)-producing CD4+ cells and CD8+ cytotoxic T-lymphocytes (CTL) are able to control and eliminate virus-infected cells." (PMID 23557172, 2013). "Besides targeting tumor cells, CD4+ effector T cells have been implicated in inhibiting tumor angiogenesis by acting on tumor stroma via IFNγ." (PMID 22400040, 2012). "Increased cell surface expression of MHC class I cell molecules, associated with upregulation of the antigen-presenting machinery-related genes, as well as of genes encoding selected components of the IFNγ-signalling pathway in tumours explanted from 5AC-treated animals, were observed." (PMID 22015556, 2011). "Based on these findings, we hypothesized that in vivo selection of developing tumor clones would be associated with the ability of tumor cells to overexpress the IFN/STAT1 pathway while resisting IFNγ-mediated cytotoxicity." (PMID 19503789, 2009). "Moreover, GSEA results demonstrated significant enrichments of prognostic immune signatures in tumor samples after AR signaling inhibition by enza treatment, including the Hallmark IFNγ signaling signature, the 18-gene T cell–inflamed GEP, and ICR 20-gene signatures." (PMID 41486951, 2026). "Importantly, characterization of CD4+ and CD8+ T cell subpopulations in vitro showed that PTSO was able to increase those producing IFNG, thus resulting in an increase in Th1 and Tc1 subsets, which are reported to be linked to a reduction in tumor progression in CRC." (PMID 41010517, 2025). "Furthermore, most of these pathways are associated with an anti-tumor response, although the interferon-gamma and inflammatory response can have either pro- or anti-tumoral effects depending on the context, which can account for the lack of response in patients in which these changes were observed." (PMID 40585251, 2025). "Additionally, genetic alterations within the tumor cells, like mutations in the interferon - gamma pathway genes, may affect the sensitivity of tumors to ICIs even in the presence of high PD - L1 levels." (PMID 39720720, 2024). "Notably, loss of tumor IFNγ signaling sensitized many tumor models to ICB." (PMID 37492581, 2023). "Moreover, in the tumor tissue, a relative reduction in IL17a+ pro-tumor T cells and an increase in the IFNγ+ subpopulation was observed, possibly linked to a potential increase in responses to checkpoint inhibitor blockers, which is typically ineffective in PC." (PMID 37370753, 2023). "Therefore, IFNγ/CXCL10 can be linked to the anti-tumor immune response." (PMID 37445941, 2023). "Indeed, increased IFNG mRNA in tumor tissues of AOM/DSS mice receiving AAT might be linked with higher number of mice having diarrhea in this group." (PMID 37532996, 2023). "Mice that develop more colitis-associated tumors have increased numbers of CD8+IFNγ+ T cells in lamina propria with higher relative abundance of Alistipes, Ruminococcus, Prevotellaceae, and lower abundance of Lachnospiraceae in the gut compared to mice that develop low tumor burden." (PMID 37824458, 2023). "Effector CTLs can exert antigen-driven anti-tumor responses through granule exocytosis mediated by perforin and the granule-associated enzymes (granzymes), through Fas ligand (FasL) induced apoptosis, or indirectly through secreted cytokines such as interferon γ (IFNγ)." (PMID 37582744, 2023).
tumor (continued). "This would make IFNγ a promising strategy in the case of relatively ‘’immune cold’’ cancers, such as metastatic castration-resistant prostate cancer (mCRPC), which is characterized by a low tumor mutational burden and few tumor infiltrating T cells, and are relatively resistant to ICBs13." (PMID 35459800, 2022). "However, one study confirmed that intratumoral Tregs indirectly promote M2-like TAMs by boosting SREBP1-dependent lipid metabolism and then limiting the CD8+ T-produced interferon-gamma (IFNγ), thereby leading to tumor progression and orchestrating tumor-associated immunosuppression." (PMID 36203151, 2022). "In the tumor immune microenvironment, Treg cells maintain the metabolic fitness and mitochondrial integrity of M2-like tumor-associated macrophages indirectly by repressing IFNγ production derived from CD8+ T cells, which is dependent on SREBP-1 and its mediated fatty acid synthesis." (PMID 35912181, 2022). "In our recent work, we performed ICS to determine IFNγ expression, a common indicator of T cell responses, in crude spleen and lung tissue-dissociated cells as a means of assessing cancer-associated systemic immunosuppression at the early tumor progression stage." (PMID 35126389, 2022). "The hallmarks negatively correlated with stemness included interferon-alpha response, interferon-gamma response, and complement, and were the same as those identified in cluster 1.1 (cluster of genes overexpressed in subtype 1 and associated with the tumor microenvironment)." (PMID 34552068, 2021). "In this context, according to previous studies, inhibition of IFNγ production may cause further immunologic effects such as inhibition of the development of T helper 1 (Th1) cells, maturation of DC cells and stimulation of tumor growth and metastatic process." (PMID 33435455, 2021). "However, IFNγ has been associated with both anti-tumor and pro-tumor effects." (PMID 33732652, 2021). "In addition to reflecting the spontaneous immune-activated status of the tumor, gene signatures related to IFNG response are widely associated with the expression of immune checkpoints, tumor mutational burden (TMB), responsiveness to immunotherapy, and clinical outcomes of various cancers." (PMID 34566988, 2021). "However, it still remains unclear if tumor-specific CTLs can have deficient IFNγ responses and the factors contributing to the deficiency." (PMID 32194559, 2020). "Furthermore, it was shown that IFNγ–EVs could decrease the anti-inflammatory phenotype of tumour-associated myeloid cells and, consequently, significantly decreases the tumour size and neurotoxicity in the brains of mice with glioma." (PMID 32366909, 2020). "Although the cellular mechanisms have not been fully elucidated, truncating somatic JAK1 mutations in gynecological carcinomas reduced IFNγ-induced MHC class I expression at the tumor cell surface, which could reduce immune recognition and facilitate immune evasion." (PMID 31552026, 2019). "Thus, tumour cells that are resistant to caspase-mediated cell death, including GBMs that overexpress Bcl-2, might be more sensitive to granzyme A. IFNγ has also previously been implicated in the modulation of levels of HLA ligands." (PMID 31319548, 2019). "Therefore, EGFR blockade may not only diminish the tumor cell intrinsic EGFR-induced PD-L1 upregulation but also the cell extrinsic IFNγ-mediated signals that have been associated with CD8+ T cell infiltration in the TME." (PMID 28611673, 2017). "Interestingly, a direct correlation existed between the extent of the tumor specificity obtained ex vivo and the clinical outcomes of the patients – higher tumor specificity and increased production of both IL-2 and IFNγ of the ex vivo product was associated with CRs." (PMID 27066005, 2016). "Additionally, the Th1 cytokine IFNγ was implicated in tumor immune surveillance in mice." (PMID 21846333, 2011).
tumor (continued). "First, the in ovo activation of CAR-T cells and their functionality in the tumor were investigated through the intra-tumoral gene expression of human IFNγ and human TNFα by RT-qPCR at EDD18." (PMID 41596451, 2026). "Consistently, in vivo neutralization of IL-2 alongside Treg depletion abrogates the induction of IFNγ+ γδ T cell responses, whereas administration of an IL-2Rβγc agonist circumvents Treg-mediated suppression and enhances tumor control." (PMID 42126428, 2026). "In vivo, GALNT7 knockdown reduced tumor growth, enhanced CD8+ T cell infiltration, and increased interferon gamma (IFN-γ) production within the tumor microenvironment." (PMID 42318657, 2026). "As monotherapy, rHER2 ECD mRNA-LNPs induced high anti-HER2 antibody titers, polyfunctional CD8+ T cells (IFNγ+/TNFα+), and durable memory T cells, achieving 87.0% tumor inhibition." (PMID 41993212, 2026). "These lymphocytes kill some tumor cells and produce cytokines, including IFNγ, that activate macrophages and other antigen-presenting cells, and chemokines that recruit immune cells to the tumor." (PMID 41315764, 2026). "After 4 h exposure to tumour cells, production of the cytokines IFNγ and TNF was significantly increased in T cells from clusters compared with in T cells from singlets, indicative of higher activation." (PMID 41261135, 2026). "Resistance arose from upregulated drug efflux transporters and impaired endosomal processing in CD30+ malignant T cells, while CD30- tumor cells showed blunted IFNα and IFNγ responses." (PMID 41762706, 2026). "Leveraging a unique dataset with matched biopsies before and after AR inhibition with enza treatment, we identified enriched immune cell signaling pathways and IFNγ signaling activity in the patients’ on-treatment tumor samples that showed AR deactivation." (PMID 41486951, 2026). "G-CSF stimulated neutrophils have been shown to contribute to the anti-tumor immune response via upregulation of unconventional T cells, maintenance of interferon gamma- based immunity, and direct tumor cell killing in some models." (PMID 41716400, 2026). "Tumor evolution impaired pathways related to protein folding and chromosome localization, whereas leucine modulated interferon-gamma and hydrogen peroxide responses." (PMID 42135921, 2026). "Despite its anti-tumor effects, IFNγ can also induce the expression of PD-L1 and indoleamine 2,3-dioxygenase (IDO) and can therefore contribute to the tumor’s escape from immune surveillance and allow tumor progression." (PMID 41596451, 2026). "It is well established that interferon gamma and other proinflammatory cytokines in hot tumor microenvironments drive PD-L1 expression on tumor cells." (PMID 41456573, 2026). "Lytic IFNγ is present in tumor-infiltrating CTLs and is cosecreted with granzyme B (GzmB) in both soluble form and as part of supramolecular attack particles (SMAPs)." (PMID 41781697, 2026). "Instead, these lymphocytes control tumor growth via secretion of IFNγ, as depletion of IFNγ inhibited the therapeutic effect of CD40 agonist." (PMID 41676732, 2026). "To further assess the local immune activation within the tumor microenvironment, we performed immunohistochemical staining for granzyme B and interferon-gamma (IFN-γ)." (PMID 41541271, 2026). "Second, APAP directly impairs effector T-cell function by suppressing interferon-gamma (IFN-γ) production—a key cytokine essential for antitumor immunity, antigen presentation, and tumor cell killing." (PMID 41357190, 2025). "This immunogenic, non-apoptotic form of cell death stimulates the release of interferon-gamma (IFN-γ) and various inflammatory cytokines and exposes tumor-specific neoantigens generated by oncolytic activity." (PMID 41294877, 2025). "ReoV-loaded LAKDC and iDC were found to shield ReoV from NAb and facilitate tumor cell killing, create a proinflammatory cytokine environment (IFNγ, IL-12, IFNα, and TNFα), and induce an antitumor immune response." (PMID 40005517, 2025).
tumor (continued). "Lactic acidosis inhibits NFAT, reduces the production of IFNγ, and downregulates PPARγ, limiting the cell cytolytic function of NK cells and promoting tumor progression." (PMID 40236700, 2025). "L. reuteri promotes the activation of anti-tumor CD8+ IFNγ+ T cells by releasing indole-3-aldehyde (I3A)." (PMID 40431165, 2025). "To demonstrate that membrane-bound antigen uptake also leads to subsequent antigen presentation, we co-cultured antigen-specific B and T cells in the presence of Caski + mbE6 tumor cells and performed intracellular IFNγ staining." (PMID 40808959, 2025). "HLA-E protein levels are generally higher in tumor cells than in healthy tissues and available evidence indicates that IFNγ can upregulate HLA-E expression." (PMID 39706891, 2025). "Tumor‐targeted delivery of RSL‐3 nanoparticles induces immunogenic cell death while stimulating CTL IFNγ secretion." (PMID 40919133, 2025). "Given previous findings suggesting a role of HMGB1 in tumor angiogenesis, we further investigated the influence of IFNG expression on this process." (PMID 39945555, 2025). "In HCC patients, NK cells exhibit phenotypic exhaustion characterized by diminished cytotoxicity and the reduced production of IFNγ, impairing their ability to eliminate malignant hepatocytes and modulate the tumor microenvironment." (PMID 40868256, 2025). "At this point, lower PD-L1 expression can be indirectly linked to STK11 mutation due to lower T-cell activity and smaller amount of IFNγ secreted by these cells, which is known as a cytokine, inducing PD-L1 expression in STK11 mutated tumours." (PMID 40650126, 2025). "TNF-α and interferon-gamma (IFN-γ), released by immune cells, play complex roles in inflammation and tumor progression, affecting cell invasion and interactions with surrounding tissues." (PMID 40061139, 2025). "In the tumor microenvironment of the solid tumor, tumor-infiltrating lymphocytes kill cancer cells by producing cytokines, such as, interferon-gamma (IFN-γ), granzyme B, and tumor-necrosis factor-alpha (TNF-α)." (PMID 40169858, 2025). "For instance, Professor Blankenstein found that IFNG can act on endothelial cells within tumors, promoting tumor vascular contraction and disrupting the tumor's energy supply, ultimately leading to tumor regression." (PMID 39945555, 2025). "IFNγ works synergistically with EBNA2 to induce PD-L1 on EBV+ tumor cells; the immunosuppressive cytokine IL-10 acts as critical pathway in suppressing the host’s antiviral T cell response." (PMID 41516315, 2025). "Since IFNγ is one of the major immune stimulants that induce tumor cell stress, our results suggest that METTL5 continues to regulate ATF4 translation in OC cells even under the immune attack." (PMID 41042068, 2025). "Our findings revealed a significant enhancement in IFNγ production when N2a tumor cells were co-cultured with splenocytes trained with BET/JQ1, with an even greater enhancement observed when combined with C-170." (PMID 40552293, 2025). "CpG, in turn, has been demonstrated to enhance Th1-immune responses by increasing the production of anti-tumor cytokines, such as IFNγ and TNF-α." (PMID 40918451, 2025). "We concluded that anti-CTLA-4 antibodies prune tumor endothelial cells and upregulate the PD-L1 immune checkpoint on TA-HEVs via Fc- and IFNγ-dependent mechanisms." (PMID 40460830, 2025). "Metabolic challenges further compound these issues, as tumor-derived lactic acid suppresses PPARγ expression in iNKT, impairing IFNγ production and anti-tumor function." (PMID 40718496, 2025). "Compared to the iRFA-treated group, the addition of Nano-IFNγ/Zole altered the tumor immune microenvironment." (PMID 39776793, 2025). "PD-L1 is broadly expressed on tumor cells, antigen-presenting cells (APC), and stromal cells within the tumor microenvironment, with its expression regulated by Interferon-gamma (IFN-γ)." (PMID 40535343, 2025).